YPEL3 (yippee like 3)
Description:
Involved in proliferation and apoptosis in myeloid precursor cells.
Synonyms: MGC10500
Tractability: PROTAC: UniProt records ubiquitination sites on it.
Gene: Protein-coding gene on chromosome 16 (30,092,314 to 30,096,915, reverse strand). Ensembl gene ENSG00000090238.
Subcellular location: Nucleus, nucleolus
Gene Ontology:
Biological process: positive regulation of cellular senescence
Cellular component: nucleolus
Genetic constraint (gnomAD): Loss-of-function variants: 5 observed, 18.62 expected, observed/expected ratio (o/e) 0.27, 90% interval 0.14 to 0.56. The upper end of that interval is the gene's LOEUF score, 0.56, which puts it in group 2 of 6, group 1 being the genes least tolerant of losing a copy. Missense variants: 155 observed, 220.07 expected, observed/expected ratio (o/e) 0.7, 90% interval 0.62 to 0.81. Synonymous variants: 87 observed, 91.68 expected, observed/expected ratio (o/e) 0.95, 90% interval 0.8 to 1.13.
Homologues: Orthologues: dog YPEL3 (97% identical), pig YPEL3 (82% identical), chimpanzee YPEL3 (76% identical), guinea pig YPEL3 (76% identical), mouse Ypel3 (76% identical), rabbit YPEL3 (76% identical), zebrafish ypel3 (68% identical), macaque YPEL3 (49% identical), rat Ypel3 (48% identical). Paralogues in human: YPEL2 (68% identical), YPEL1 (67% identical), YPEL4 (63% identical), SARDH (29% identical), YPEL5 (28% identical), DMGDH (22% identical), AMT (20% identical), PDPR (18% identical), L2HGDH (14% identical), FOXRED1 (13% identical).
Diseases named in the same sentence as YPEL3 in open-access papers:
YPEL3 is named in the same sentence as 23 diseases in open-access papers, as found by Europe PMC text mining. Sharing a sentence is not in itself a finding about the gene and the disease. The quoted sentences say what the papers report.
nasopharyngeal carcinoma (6 papers, 2016 to 2025). A carcinoma arising from the nasopharyngeal epithelium. "In nasopharyngeal cancer cells, YPEL3 promotes E-cadherin expression by inhibiting the entry of β-catenin into the nucleus, and inhibits vimentin expression to regulate the EMT process, YPEL3 also inhibits cell proliferation and migration." (PMID 36359097, 2022). "In breast, lung, colon, ovarian, and nasopharyngeal carcinoma cells, YPEL3 expression is downregulated." (PMID 32544203, 2020). "Overexpression of YPEL3 in cultured cells results in cell cycle arrest and suppression of the epithelial-mesenchymal transition in nasopharyngeal carcinoma cells." (PMID 32544203, 2020). "As YPEL3 can be induced by DNA damage and YPEL3 inhibits EMT of nasopharyngeal carcinoma cells via Wnt/β-catenin signaling, However, the role of YPEL3 and its regulation of EMT in liver fibrosis was unknown." (PMID 40100806, 2025). "YPEL3 has been proposed to act as a negative regulator of the WNT/ß-Catenin signaling pathway by preventing ß -Catenin nuclear translocation during metastasis of nasopharyngeal carcinoma cells." (PMID 32544203, 2020).
breast carcinoma (5 papers, 2020 to 2024). "High levels of Klhl24, Hbp1, Crebrf, Ypel2, CD22 and Ypel3 were correlated with better outcomes, whereas lower levels of Gdf15, Cdc25a, Ddit4 and Psat1 were associated with better prognosis in breast cancer patients." (PMID 34990474, 2022). "The increased YPEL3 enhanced the oxygen consumption and oxidative stress in mitochondria, ultimately promoting breast cancer cell senescence and thereby resulting the apoptosis of cancer cells." (PMID 38851002, 2024). "To elucidate whether these miRNAs promote cellular senescence and death through YPEL3 upregulation, we examined their effects on cellular proliferation, SA-β-gal activity, and mitochondrial activity in human breast cancer MCF-7 cells." (PMID 39345743, 2024). "In another breast cancer study, knockdown YAP1 would activate YPEL3 via the Hippo pathway." (PMID 38851002, 2024).
schizophrenia (4 papers, 2021 to 2025). A major psychotic disorder characterized by abnormalities in the perception or expression of reality. "One of the previous studies that considered YPEL3 identified it as a pleiotropic gene jointly influencing BMI and risk of schizophrenia." (PMID 41006818, 2025). "YPEL3, involved in glial development and apoptosis, has been linked to both BMI and schizophrenia, and mouse knockdown models showing altered fat composition, according to the International Mouse Phenotyping Consortium (IMPC)." (PMID 41006818, 2025). "In contrast, another study asserted that the association between YPEL3 and schizophrenia is due to its correlation with expression of INO80E, another possible candidate gene for BMI and risk of schizophrenia in the 16p11.2 region." (PMID 41006818, 2025). "CpGs selected by CEWAS include cg06985993 and cg08213375 for YPEL3 and ZFYVE21, respectively, whose DNAm levels are associated with schizophrenia GWAS SNPs: rs3814877 and rs4900597." (PMID 34807913, 2021). "An additional gene, YPEL3, was significantly associated with schizophrenia in the negative direction (P = 4.9 × 10−6)." (PMID 34715901, 2021). "As an example, YPEL3 and ZFYVE21 are significant for schizophrenia based on CEWAS but p>0.05 based on MetaXcan." (PMID 34807913, 2021). "While most associations we detected were in the expected direction given previous knowledge, MVP and KCTD13 were associated with BMI in the opposite (positive) direction, and YPEL3 with schizophrenia in the negative direction." (PMID 34715901, 2021).
breast tumor (2 papers, 2024 to 2025). "The expression levels of MDM4, MDM2, YAP1, and YPEL3 in human breast tumor samples were investigated compared to normal samples using TNM plot analysis." (PMID 39345743, 2024).
microcephaly (2 papers, 2020 to 2022). A congenital or acquired developmental disorder in which the circumference of the head is smaller than normal for the person's age and sex. "Among the genes related to cerebellar volume in the four substructure GWASs we find genes related to ataxia (PEX7, MRPS27, PTK2), neurodevelopment (YPEL3, CASP6, TRIM11, GNB5) and microcephaly (PDCD6IP, USP28)." (PMID 35546225, 2022).
Obesity (2 papers, 2018 to 2025). Accumulation of substantial excess body fat. "YPEL3 is located at 16p11.2, a gene dense region well-known for a microdeletion associated with neurocognitive developmental delay and predisposition to obesity." (PMID 41006818, 2025). "Other model organism studies have shown alterations in YPEL3 results in altered obesity phenotypes." (PMID 41006818, 2025).
adenoma (1 paper, 2025). A neoplasm arising from the epithelium. "Among them, 3 genes (NUDT13, PYROXD2, and YPEL3) were validated through RT‐qPCR using a cohort comprising 36 paired early‐stage CRC samples and 14 paired adenomas, as well as through datasets from UCSC Xena." (PMID 39921866, 2025).
depression (1 paper, 2020). "These colocalization sites included eQTLs for YPEL3, which is highly expressed in whole blood and affects neural development, as well as PRSS16, which impacts immunologic development and has been implicated in multiple GWAS for depression phenotypes." (PMID 32600345, 2020).
fibrosis (1 paper, 2025). the formation of excess fibrous connective tissue in an organ or tissue in a reparative or reactive process. "Depletion of circABHD3 significantly reduced EMT, mitochondrial impairment and hepatic fibrosis via promoting YPEL3 expression and suppressing β-catenin signaling in vivo." (PMID 40100806, 2025).
gastric cancer (1 paper, 2020). A primary or metastatic malignant neoplasm involving the stomach. "The Kaplan–Meier plotter analysis showed high expression of the YPEL3 gene and was positively correlated with the more number of patients at high risk in Gastric cancer patients." (PMID 32943700, 2020).
Hepatic fibrosis (1 paper, 2025). The presence of excessive fibrous connective tissue in the liver. "Subsequently, circABHD3 promoted YTHDF2-dependent recognition of YPEL3 mRNA to destabilize YPEL3 mRNA to reduce its expression and activate β-catenin signaling, thus exacerbating hepatic fibrosis." (PMID 40100806, 2025). "Our study sheds novel light on the pathogenesis of hepatic fibrosis and provides potential therapeutic targets such as circABHD3, YPEL3 and β-catenin signaling." (PMID 40100806, 2025). "MEOX1-mediated generation of circABHD3 promotes EMT and mitochondrial impairment by enhancing YTHDF2-mediated degradation of YPEL3 mRNA and activating downstream β-catenin signaling, thus exacerbating hepatic fibrosis." (PMID 40100806, 2025). "CircABHD3 promotes EMT and mitochondrial impairment via facilitating YTHDF2-mediated degradation of YPEL3 mRNA and activating downstream β-catenin signaling, thus exacerbating hepatic fibrosis." (PMID 40100806, 2025). "The suppressive role of YPEL3 in β-catenin signaling indicates that YPEL3 may be involved in hepatic fibrosis." (PMID 40100806, 2025). "Thus, depletion of circABHD3 suppressed CCl4-induced hepatic fibrosis dependent on YPEL3 upregulation and subsequent suppression of β-catenin signaling in mice." (PMID 40100806, 2025). "Thus, circABHD3 might destabilize YPEL3 mRNA and inhibit its expression, thereby activating β-catenin signaling in hepatic fibrosis." (PMID 40100806, 2025). "Taken together, we firstly demonstrated that MEOX1-regulated circABHD3 exacerbated hepatic fibrosis via promoting EMT and mitochondrial through suppression of YPEL3-mediated inactivation of β-catenin signaling in a YTHDF2-dependent manner." (PMID 40100806, 2025). "We found that circABHD3 facilitated the decay of YPEL3 mRNA in a m6A/YTHDF2 dependent manner, leading to GSK-3β downregulation and inactivation of β-catenin signaling in liver fibrosis." (PMID 40100806, 2025). "Therefore, circABHD3 destabilized YPEL3 mRNA through YTHDF2 in a m6A-dependent manner, thus promoting EMT and hepatic fibrosis." (PMID 40100806, 2025).
neurofibromatosis type 1 (1 paper, 2021). A clinically heterogeneous, neurocutaneous genetic disorder characterized by cafe-au-lait spots, iris Lisch nodules, axillary and inguinal freckling, and multiple neurofibromas. "Given that this patient's mesenteric plexiform neurofibroma is associated with YPEL3 dysfunction, she is unlikely to benefit from MEK inhibitors, which are the newly approved treatment for inoperable plexiform neurofibroma in patients with neurofibromatosis type 1." (PMID 37205972, 2021).
neuropathy (1 paper, 2020). A disorder affecting the nervous system that manifests with pain, tingling, numbness, and/or muscle weakness. "Identification of additional patients with YPEL3 mutations and overlapping phenotypes will provide further confidence that YPEL3 is a neuropathy gene." (PMID 32544203, 2020). "We used zebrafish as a model system to validate that YPEL3 mutations are causative of neuropathy." (PMID 32544203, 2020).
ovarian carcinoma (1 paper, 2020). A malignant neoplasm originating from the surface ovarian epithelium. "Kaplan–Meier plotter analysis revealed that the deregulation of YPEL3 gene had antagonistic effects on the survival rate of gastric and ovarian cancer patients." (PMID 32943700, 2020). "The YPEL3 gene was thus found to be an important prognostic marker in case of Gastric and Ovarian cancer patients." (PMID 32943700, 2020). "However, in Ovarian cancer patients, a significant decrease in the number of risks (more survival rate) with high expression of YPEL3 gene was observed." (PMID 32943700, 2020). "It is evident from the results that YPEL3 gene expression was not linked with the gender of the cancer patients as both Breast and Ovarian cancers are gender-specific but only Ovarian cancer patients showed a significant correlation with YPEL3 gene deregulation." (PMID 32943700, 2020). "This correlation of YPEL3 deregulation with gastric and ovarian cancer may have an indirect relation with the predicted damaging mutations in YPEL3 gene." (PMID 32943700, 2020).
tumor (16 papers, 2016 to 2025). "Induction of YPEL3 causes permanent growth arrest, cellular senescence, and inhibition of metastasis in normal and tumor cells." (PMID 34675221, 2021). "We report for the first time that miR-34a and miR-605-5p function as tumor suppressors by upregulating YPEL3 and downregulating YAP1 expression." (PMID 39345743, 2024). "YAP1 expression was also high in the tumor samples, but YPEL3 levels were relatively lower in the tumor samples than in the normal samples." (PMID 39345743, 2024). "In the present study, we confirmed that miR-34a and miR-605-5p act as tumor suppressors and upregulate YPEL3 expression by inhibiting YAP1 expression." (PMID 39345743, 2024). "Taking the in vitro and in vivo results together, it was shown that Txnip, Aox1, Per3 and Ypel3 were consistently upregulated in both tumor lines and Acat2, Clspn and Ercc6l were downregulated." (PMID 33407762, 2021). "YPEL3 codes for Yippee-like 3, a protein that suppresses tumor growth, proliferation and metastasis in several types of cancer." (PMID 31461406, 2019). "A number of studies have demonstrated that YPEL3 suppresses tumor growth, proliferation and metastasis in several types of cancer, such as in breast tumors and colon tumors." (PMID 27400785, 2016). "The present study confirms that YPEL3 is an important tumor suppressor in NPC and has identified novel YPEL3/Wnt/β-catenin signaling in NPC metastasis." (PMID 27400785, 2016). "YPEL3 has been reported to inhibit tumor proliferation, metastasis and growth, but its roles in hepatic fibrosis are unknown." (PMID 40100806, 2025). "Therefore, the expression of Il6, Nos2, Ccl2, Spp1, Tnf, Acat2, Aox1, Crem, Gls2, Per3, Pink1, Txnip, and Ypel3 was examined in acidosis upon simultaneous transfection with microRNA mimics or antagomirs in two tumor lines in vitro and in vivo." (PMID 38069241, 2023). "YPEL3 is a tumor suppressor that can inhibit the EMT process in a variety of tumor cells." (PMID 36359097, 2022). "Current research suggests that Ypel3 is a gene that inhibits tumor proliferation, suggesting that it may be a promising anti-cancer target protein." (PMID 32599940, 2020). "Investigation of these polymorphisms at the protein level and its potential biological effect is necessary as YPEL3 down regulation in various tumor conditions could prove it to be an important molecular target for anti-cancer therapies." (PMID 32943700, 2020). "YPEL3 that induces cellular senescence in both normal and tumour cells of humans may show altered expression under the influence of incidental mutations." (PMID 32943700, 2020). "Additional markers of senescence can include Yippee-like-3 (YPEL3) expression, a tumor suppressor that is induced by DNA damage and downregulation of Lamin B1 expression." (PMID 38567308, 2024). "YPEL3, first identified as SUAP, is classified as a tumor suppressor for two reasons." (PMID 27400785, 2016).
cancer (9 papers, 2016 to 2025). A tumor composed of atypical neoplastic, often pleomorphic cells that invade other tissues. "Due to inadequate information about the structure and the impact of variants in YPEL3 protein, limited attempts are made to explore the précised medicines facilitating cure for several cancers in the context of mutation driven alteration in the structure and function of the protein." (PMID 32943700, 2020). "Collectively, the results of the present study indicate that the miRNAs-YAP1/YPEL3 cascade can be activated to protect cancer promotion." (PMID 39345743, 2024). "In human colon cancer tissues, YPEL3 also suppresses cancer cell proliferation, migration and invasion by inhibiting the Wnt/β-catenin signaling pathway, which controls many biological phenomena, such as fat metabolism and animal development." (PMID 36359097, 2022). "In addition, YPEL3, a member of the putative zinc finger motif, is emerging as a negative regulator of β-catenin signaling to suppress EMT in cancer." (PMID 40100806, 2025).
peripheral neuropathy (1 paper, 2020). A disorder affecting the peripheral nervous system. "Our interest in YPEL3 arose from a patient with a variant of unknown significance in this gene who displays unique clinical features including central hypomyelination and peripheral neuropathy." (PMID 32544203, 2020).
YPEL3 also shares sentences with these, for which no sentence is quoted: Ataxia (1 paper); hematological malignancies (1); neurological disease (1); osteosarcoma (1); pancreatic adenocarcinoma (1); plexiform neurofibroma (1).